RAPGEF1 (Rap guanine nucleotide exchange factor 1)
Description:
Guanine nucleotide-releasing protein that binds to SH3 domain of CRK and GRB2/ASH. Transduces signals from CRK to activate RAS. Involved in cell branching and adhesion mediated by BCAR1-CRK-RAPGEF1 signaling and activation of RAP1. Plays a role in the establishment of basal endothelial barrier function. Plays a role in nerve growth factor (NGF)-induced sustained activation of Rap1 and neurite outgrowth.
Synonyms: GRF2; C3G
Tractability: Antibody: its Gene Ontology location is reachable by antibodies, with medium confidence. PROTAC: UniProt records ubiquitination sites on it; ubiquitination databases record sites on it; its protein half-life has been measured.
Gene: Protein-coding gene on chromosome 9 (131,576,758 to 131,740,117, reverse strand). Ensembl gene ENSG00000107263.
Subcellular location: Early endosome
Subcellular location (Human Protein Atlas): Vesicles
Pathways (Reactome):
Signal Transduction: Downstream signal transduction; Erythropoietin activates RAS; Frs2-mediated activation; MET activates RAP1 and RAC1; RAC3 GTPase cycle
Immune System: Regulation of signaling by CBL
Gene Ontology:
Molecular function: guanyl-nucleotide exchange factor activity; protein binding
Biological process: cellular response to cAMP; cellular response to nerve growth factor stimulus; establishment of endothelial barrier; nerve growth factor signaling pathway; positive regulation of GTPase activity; positive regulation of neuron projection development; Rap protein signal transduction; regulation of cell junction assembly; cell surface receptor protein tyrosine kinase signaling pathway; Ras protein signal transduction; signal transduction; small GTPase-mediated signal transduction
Cellular component: cytoplasm; early endosome; cytosol; plasma membrane
Genetic constraint (gnomAD): Loss-of-function variants: 32 observed, 133.92 expected, observed/expected ratio (o/e) 0.24, 90% interval 0.18 to 0.32. The upper end of that interval is the gene's LOEUF score, 0.32, which puts it in group 1 of 6, group 1 being the genes least tolerant of losing a copy. Missense variants: 1,198 observed, 1,614.9 expected, observed/expected ratio (o/e) 0.74, 90% interval 0.71 to 0.78. Synonymous variants: 629 observed, 668.14 expected, observed/expected ratio (o/e) 0.94, 90% interval 0.88 to 1.01.
Homologues: Orthologues: dog RAPGEF1 (92% identical), guinea pig RAPGEF1 (90% identical), rat Rapgef1 (90% identical), mouse Rapgef1 (89% identical), macaque RAPGEF1 (88% identical), chimpanzee RAPGEF1 (81% identical), pig RAPGEF1 (79% identical), rabbit RAPGEF1 (71% identical), tropical clawed frog rapgef1 (70% identical), zebrafish rapgef1b (63% identical), zebrafish rapgef1a (61% identical), Drosophila melanogaster C3G (34% identical), and 1 more. Paralogues in human: RAPGEF4 (14% identical), RAPGEF2 (14% identical), RAPGEF6 (13% identical), RASGRF1 (13% identical), RASGRF2 (13% identical), SOS1 (12% identical), SOS2 (12% identical), RAPGEF3 (12% identical), RAPGEF5 (11% identical), RALGDS (11% identical), RGL3 (10% identical), RGL1 (9% identical), and 12 more.
Diseases named in the same sentence as RAPGEF1 in open-access papers:
RAPGEF1 is named in the same sentence as 68 diseases in open-access papers, as found by Europe PMC text mining. Sharing a sentence is not in itself a finding about the gene and the disease. The quoted sentences say what the papers report.
melanoma (4 papers, 2017 to 2026). A malignant, usually aggressive tumor composed of atypical, neoplastic melanocytes. "Further, we show RAPGEF1 expression is significantly enriched in melanomas lacking strongly activating RAS-MAPK mutations, suggesting that RAPGEF1 may promote oncogenic RAS-MAPK signaling in melanomas." (PMID 42100918, 2026).
type 2 diabetes (3 papers, 2009 to 2017).
hepatocellular carcinoma (2 papers, 2021 to 2025). A malignant tumor that arises from hepatocytes. "In HCC (hepatocellular carcinoma), the analyses of public databases indicate that RAPGEF1 mRNA levels gradually increase in HCC patient samples during HCC progression up to stage III, which is associated with a reduced overall patient survival." (PMID 34576182, 2021).
B-cell lymphoma (1 paper, 2025). "To achieve this, we introduced the activating Y564H point mutation into the Rapgef1 gene in the A20 mouse B-cell lymphoma line using the CRISPR/Cas9 gene editing system with HDR." (PMID 41299498, 2025).
bladder cancer (1 paper, 2016). "In growth factor mediated intracellular pathways, RAPGEF1 rs7040470 was significantly associated with bladder cancer risk and the significance level reached 1.2×10−5 in the pooled analysis." (PMID 27738493, 2016).
cervical carcinoma (1 paper, 2021). A carcinoma arising from either the exocervical squamous epithelium or the endocervical glandular epithelium. "For instance, RAPGEF1 (also known as C3G, endometrial cancer) is frequently hypermethylated in cervical carcinoma and consequently inactivated." (PMID 34313788, 2021).
cervical squamous cell carcinoma (1 paper, 2024). A squamous cell carcinoma arising from the cervical epithelium. "RAPGEF1 encodes a member of the Ras family of small GTPases and exerts anticancer effects, which was associated with promoter hypermethylation in cervical squamous cell carcinoma." (PMID 38672263, 2024).
COVID-19 (1 paper, 2022). A disease caused by infection with severe acute respiratory syndrome coronavirus 2. "A decrease in the expression of the following genes was also observed in COVID-19-positive patients: RAPGEF1 (p = 0.0091), MAP2K1 (p = 0.038), CEBPB (p = 3.3 × 10−6), STAT6 (p = 0.041), JUN (p = 1.4 × 10−8), PRKACA (p = 0.021), and AKT1 (p = 1.3 × 10−6)." (PMID 36298734, 2022).
liver cancer (1 paper, 2023). An epithelial or non-epithelial malignant neoplasm that arises from the liver. "In addition to C3G upregulation, genomic databases analyses show that RapGEF1 is commonly altered in liver cancer (HCC and CCA)." (PMID 38138981, 2023). "The role of C3G/RAPGEF1, required for the proper function of HGF/MET signaling in HCC and HPCs, is highlighted, due to its ability to promote HCC growth and, regulate HPC fate and platelet-mediated actions on liver cancer." (PMID 38138981, 2023).
mastitis (1 paper, 2021). Inflammation of breast tissue during lactation or postpartum due to an obstructed duct or infection. "RAPGEF1, the significant gene for the PELT treatment, has been studied and found to be related to persistence of lactation and mastitis in dairy cows also to the lipomatous myopathy disease in Piedmontese cattle." (PMID 34887899, 2021).
non-alcoholic fatty liver disease (1 paper, 2022). "Hence, the analysis of data from public databases indicate that RapGEF1 mRNA expression decreased in liver samples from non-alcoholic fatty liver disease (NAFLD) and non-alcoholic steatohepatitis (NASH) patients compared to healthy livers." (PMID 36263169, 2022).
non-Hodgkin lymphoma (1 paper, 2025). Distinct from Hodgkin lymphoma both morphologically and biologically, non-Hodgkin lymphoma (NHL) is characterized by the absence of Reed-Sternberg cells, can occur at any age, and usually presents as a localized or generalized lymphadenopathy associated with fever and weight loss. "The Y554H mutation in the human RAPGEF1 gene has been associated with the development of non-Hodgkin’s lymphomas." (PMID 41299498, 2025).
psoriasis (1 paper, 2023). An autoimmune condition characterized by red, well-delineated plaques with silvery scales that are usually on the extensor surfaces and scalp. "The expression of SRC and RAPGEF1 was further investigated in pathologies exhibiting keratinocyte hyperproliferation and involving miR-203, such as psoriasis and NMSC." (PMID 37635193, 2023). "We could then hypothesize that SRC and RAPGEF1 could participate in keratinocyte hyperproliferation in psoriasis." (PMID 37635193, 2023). "As miR-203 is also involved in skin diseases where keratinocytes are hyperproliferating, such as psoriasis and NMSC, BCC and SCC, this raised the question of the role of SRC and RAPGEF1 in these pathologies." (PMID 37635193, 2023).
Tourette syndrome (1 paper, 2026). A neurologic disorder caused by defective metabolism of the neurotransmitters in the brain. "Both genes contribute to a protein interaction network including ERBB4 and RAPGEF1 which we had previously identified in a large Tourette Syndrome pedigree." (PMID 42078338, 2026).
tumor (18 papers, 2009 to 2025). "A downregulation of RAPGEF1 mRNA levels in human GBM tumours and a decrease in C3G protein levels in GBM cells have recently been discovered." (PMID 34576182, 2021). "Further, AKT1 and RAPGEF1 were affected by phosphorylation, and MTOR is mutated to regulate downstream proteins involved in oncogenesis and tumor invasion." (PMID 31126066, 2019). "Hence, high RapGEF1 mRNA levels correlate with tumor progression and a lower patient survival rate." (PMID 38138981, 2023).
hematologic malignancies (1 paper, 2025). "C3G (RapGEF1) is a guanine nucleotide exchange factor that activates Rap1, a small GTPase implicated in hematologic malignancies." (PMID 41299498, 2025).
RAPGEF1 also shares sentences with these, for which no sentence is quoted: cancer (17 papers); breast carcinoma (10); infection (5); glomerular disease (4); neuroblastoma (4); colon carcinoma (3); colorectal cancer (3); diabetes (3); glioblastoma (3); glomerulonephritis (3); chronic myeloid leukemia (2); gastric cancer (2); glioma (2); kidney disease (2); Lewis lung carcinoma (2); lymphoma (2); monoclonal gammopathy (2); Alzheimer disease (1); atherosclerosis (1); atypical hemolytic-uremic syndrome (1); cardiovascular diseases (1); cerebral palsy (1); colorectal adenocarcinoma (1); endometrial cancer (1); epilepsy (1); epithelial ovarian cancer (1); glomerulopathies (1); head and neck squamous cell carcinoma (1); Hypertension (1); IgA nephropathy (1).
A further 22 diseases each share a sentence with RAPGEF1 in 1 paper.